TREM1 (triggering receptor expressed on myeloid cells 1)
Diseases named in the same sentence as TREM1 in open-access papers (continued):
Sharing a sentence is not in itself a finding about the gene and the disease.
colorectal tumor (2 papers, 2017 to 2020). "While Trem1+/+ tumors exhibited a transcriptional pattern typically associated with the inflammatory microenvironment of colorectal tumors, the immune signature of Trem1−/− mice was reminiscent of the Tfh/B cell axis that has previously been associated with a favorable prognosis in human CRC6." (PMID 29093489, 2017). "TREM1-/- mice exhibited reduced tumor number and load in an experimental model of inflammation-driven tumorigenesis of colorectal tumor." (PMID 32765489, 2020). "Collectively, our findings demonstrate a clear role of TREM-1 for intestinal tumorigenesis and indicate TREM-1-expressing neutrophils as critical players in colorectal tumor development." (PMID 29093489, 2017). "Compared to adjacent tumor-free colonic mucosa, expression of Trem1 was increased in murine and human colorectal tumors." (PMID 29093489, 2017). "We next sought to determine whether TREM-1 is expressed in human colorectal tumors and whether TREM-1 expression in human CRC would also associate with neutrophils." (PMID 29093489, 2017). "In line with the microbial-driven neutrophilic inflammation that is induced by DSS treatment, we demonstrate here that in murine colorectal tumors TREM-1 is mainly expressed by neutrophils, which also represent the predominant myeloid cell population in Trem1+/+ tumors." (PMID 29093489, 2017). "In view of the proposed significance of TREM-1 expression by macrophages in distinct types of cancer, it is intriguing that in murine colorectal tumors Ly6C− MHCII+ TAMs were evidently TREM-1 negative." (PMID 29093489, 2017). "This appeared to be a consistent trait and did not reflect a premature time-point of analysis since in more advanced and larger colorectal tumors TAMs equally lacked TREM-1 expression (data not shown)." (PMID 29093489, 2017). "Although the upregulated expression of neutrophil-specific chemokines may only be an indirect consequence of TREM-1 signaling, these data thus provide circumstantial evidence for a TREM-1-dependent recruitment of neutrophils into colorectal tumors in the AOM/DSS model." (PMID 29093489, 2017).
corneal disease (2 papers, 2016 to 2024). "Blocking TREM1 in a mouse model of P. aeruginosa keratitis resulted in a reduction of corneal disease severity." (PMID 38694515, 2024). "Furthermore, HE staining confirmed that infected corneas of control group exhibited the most serious stromal swelling, with many inflammatory cells infiltrating the stroma and anterior chamber, while inhibition of TREM-1 or Dection-1 reduced corneal disease." (PMID 26963514, 2016).
disc degeneration (2 papers, 2022 to 2025). "Chondrocytes 2 expressing MGP, MT1G, and GPX3 may play a role in reversing calcification and degeneration, and chondrocytes 4 expressing PTGES, TREM1, and TIMP1 may play a role in disc degeneration pain and inflammation." (PMID 35874809, 2022).
endocarditis (2 papers, 2018 to 2025). Inflammation of the endocardium. "Additionally, TREM-1 is linked to an increased risk of endocarditis." (PMID 41226426, 2025). "In endocarditis, several TREM-1 SNPs have been reported to be associated with endocarditis susceptibility in Caucasians, but it does not have any effect on the outcome of endocarditis." (PMID 30205488, 2018).
fungal keratitis (2 papers, 2014 to 2016). "The expression of TREM-1 and Dectin-1 increased significantly and correlated positively with the progression of fungal keratitis." (PMID 26963514, 2016). "To summarize, this study firstly demonstrated that blockage of TREM-1 and Dectin-1 can reduce the severity of corneal damage in a mouse model of fungal keratitis by downregulating the inflammatory response." (PMID 26963514, 2016). "In this study, we find that blockage of TREM-1 and Dectin-1 can alleviate fungal keratitis by modulating Th1/Th2 immune responses." (PMID 26963514, 2016). "In a mouse model of fungal keratitis, we blocked TREM-1 and Dectin-1 simultaneously and observed that the clinical scores were lower than those in other groups in which TREM-1 or Dectin-1 was inhibited alone." (PMID 26963514, 2016). "TREM-1 and Dectin-1 function concurrently in the corneal innate immune response by regulating inflammatory cytokine expression in fungal keratitis." (PMID 26963514, 2016). "Thus, it is possible that other key molecules aside from TREM-1 act simultaneously to mediate pathogenesis in fungal keratitis." (PMID 26963514, 2016). "Furthermore, inhibiting the expression of TREM-1 and Dectin-1 can exert anti-inflammatory effects and has promising potential for treatment of fungal keratitis." (PMID 26963514, 2016). "This may explain why blocking TREM-1 and Dectin-1 together can alleviate fungal keratitis more effectively." (PMID 26963514, 2016). "This study suggests that TREM-1 and Dectin-1 may have potential applications as targets for therapeutic intervention in fungal keratitis." (PMID 26963514, 2016). "Based on these studies, we hypothesized that TREM-1 and Dectin-1 may show similar increasing trends and act synergistically in fungal keratitis." (PMID 26963514, 2016). "Here, we investigate the expressions and functions of TREM-1 and Dectin-1 in fungal keratitis." (PMID 26963514, 2016). "TREM-1 expression dramatically increased in the human corneas with fungal keratitis." (PMID 25464008, 2014). "FK506 may inhibit the inflammation induced by fungi and alleviate the severity of corneal damage at an early stage of fungal keratitis by downregulating TREM-1 expression." (PMID 25464008, 2014). "However, the role of TREM-1 in fungal keratitis is largely unknown." (PMID 26963514, 2016).
inflammatory skin disease (2 papers, 2018 to 2024). Inflammatory skin disorders covers a broad category that includes many conditions ranging in severity, from mild itching to grave medical health complications These disorders are common in people of all ages and races. "It is tempting to speculate that the axis of miR-193b, miR-671, and TREM-1 is a potential candidate to the development of new tools to manage this disease and other inflammatory skin disorders." (PMID 29670621, 2018). "To evaluate the extent to which the 16-gene TREM1 myeloid signature was tumor-specific, we merged the myeloid populations from BCC tumors with existing scRNA-Seq datasets from healthy individuals, individuals with a variety of inflammatory skin diseases, and patients with different types of cancer." (PMID 39289380, 2024).
lung adenocarcinoma (2 papers, 2014 to 2025). A carcinoma that arises from the lung and is characterized by the presence of malignant glandular epithelial cells. "Since our data demonstrates that TREM-1 is expressed in tumor associated macrophages in human lung adenocarcinoma we developed an in vitro co-culture model to determine if the expression of TREM-1 in TAM in the tumor is specifically related to the tumor cells." (PMID 24842612, 2014).
lung squamous cell carcinoma (2 papers, 2016 to 2021). "We also examined TREM-1 expression in tumor tissues, including tongue carcinoma (originating from SE) and squamous cell lung cancer (originating from metaplastic SE)." (PMID 27409178, 2016). "TREM-1 was strongly expressed in the cytoplasm and nuclei in squamous cell lung cancer, while absent in tongue carcinoma." (PMID 27409178, 2016).
lymphoma (2 papers, 2013 to 2018). A malignant (clonal) proliferation of B- lymphocytes or T- lymphocytes which involves the lymph nodes, bone marrow and/or extranodal sites. "We analyzed PMNs from healthy donors or lymphoma patients for oxidative burst, phagocytosis, activation markers and IL-8 release upon TREM-1 or TLR ligation ex vivo." (PMID 29615799, 2018). "BTK and PLCγ are functionally connected, as knockdown of BTK resulted in reduced PLCγ phosphorylation in response to stimulation of the TREM-1/DAP12 pathway in a lymphoma cell line." (PMID 23825946, 2013).
mastitis (2 papers, 2013 to 2025). Inflammation of breast tissue during lactation or postpartum due to an obstructed duct or infection. "Moreover, CD40 and TREM1 signaling pathways appear as the most interesting candidates that likely provide the link between TLR2- and NLR-mediated signal transduction determining optimal host defence during mastitis." (PMID 24341851, 2013). "In addition to TNFa and IL-1b, CASP1 and NFKB1 were found to be up-regulated in our study suggesting that TREM1 signaling may likely provide the link between TLR2- and NLR-mediated signal transduction in cytokine-induced inflammation during the initiation of host defense such as in mastitis." (PMID 24341851, 2013).
multiple sclerosis (2 papers, 2013 to 2025). A progressive autoimmune disorder affecting the central nervous system resulting in demyelination. "Notable activated pathways included multiple sclerosis, triggering receptor expressed on myeloid cells‐1 (TREM1), pathogen‐induced cytokine storm, and pyroptosis signaling." (PMID 40255128, 2025).
myocardial ischemia (2 papers, 2020 to 2026). A disorder of cardiac function caused by insufficient blood flow to the muscle tissue of the heart. "Therefore, TREM-1 may represent a promising therapeutic target for the treatment of myocardial ischemia-reperfusion injury." (PMID 41511954, 2026). "Relevant preclinical data have also been obtained using the TREM-1 antagonist peptide, LR12, mimicking a conserved sequence across TREM-1 and the related receptor, TREM-like transcripts-1, in animal models of septic shock and myocardial ischemia." (PMID 32456204, 2020). "Through in vitro hypoxia-reoxygenation (H/R) model of HL-1 cardiomyocytes and in vivo myocardial ischemia-reperfusion (I/R) model of C57BL/6 mice, this study systematically explored the role and molecular mechanism of triggering receptor expressed on myeloid cells-1 (TREM1) in MIRI." (PMID 41511954, 2026).
nephritis (2 papers, 2016 to 2021). Inflammation of renal tissue. "To determine whether TREM-1 played a pathogenic role in anti-GBM-induced nephritis, we treated 129/SvJ mice with an antagonistic TREM-1 peptide, LP17." (PMID 27083877, 2016). "Our studies are the first to demonstrate the elevated expression of renal TREM-1 in the nephritis-prone 129/SvJ strain and indicate that TREM-1 plays a critical role in the pathogenesis of inflammatory nephritis." (PMID 27083877, 2016). "The current study demonstrates that the LP17 inhibitory peptide targeting TREM-1 profoundly subdues anti-GBM-mediated nephritis." (PMID 27083877, 2016). "The current studies demonstrate that anti-GBM nephritis is associated with increased expression of TREM-1 (CD354) protein and mRNA in renal tissue from the 129x1/SvJ mouse strain in contrast to the nephritis resistant B6 strain." (PMID 27083877, 2016). "further indicated that TREM-1 has the therapeutic value in anti-GBM-induced nephritis." (PMID 34176389, 2021). "This study was designed to determine whether the novel inhibitory peptide LP17, targeting the CD354 receptor, Triggering Receptor Expressed on Myeloid Cells-1 or TREM-1, could impact anti-GBM nephritis." (PMID 27083877, 2016).
ovarian carcinoma (2 papers, 2019 to 2025). A malignant neoplasm originating from the surface ovarian epithelium. "In summary, our observations demonstrated that TREM1 is upregulated in ovarian cancer, and its elevated expression level is related to poor prognosis and clinical characteristics." (PMID 39744496, 2025). "Firstly, we obtained the conclusions mostly through bioinformatics and public databases, the specific expression level of TREM1 and its role in ovarian cancer remains to be studied." (PMID 39744496, 2025). "This group was also enriched for the upstream activators PDGF BB and TREM1 and the diseases, breast, pancreatic or ovarian cancer and seizure disorders." (PMID 31221130, 2019). "However, the role of TREM1 in ovarian cancer (OV) remains unclear." (PMID 39744496, 2025).
pancreatic ductal adenocarcinoma (2 papers, 2025). An infiltrating adenocarcinoma that arises from the epithelial cells of the pancreas. "In contrast, our study reveals a different role for TREM-1 in the context of pancreatic ductal adenocarcinoma (PDAC) in immunocompetent mice." (PMID 40917508, 2025).
Pleural effusion (2 papers, 2020 to 2021). The presence of an excessive amount of fluid in the pleural cavity. "TREM-1+ DCs accumulation in pleural effusions from patients with lung adenocarcinoma also seems to be associated with disease aggressiveness and bad prognosis." (PMID 32456204, 2020).
preeclampsia (2 papers, 2022). Preeclampsia is a hypertensive disorder of pregnancy that is characterized by new-onset hypertension with proteinuria presenting after 20 weeks of gestation, and depending on mild or severe forms may initially present with severe headache, visual disturbances, and hyperreflexia. "HK2, PLOD2, and TREM1 may be associated with the development of pre-eclampsia, and their mechanisms of action in preeclampsia need to be further investigated." (PMID 36541903, 2022). "Interestingly, HK2, PLOD2, and TREM1 were significantly upregulated in the early-onset preeclampsia cohort, and TREM1 was also significantly upregulated in PE patients with concomitant hemolysis, elevated liver enzymes and low platelets (HELLP) complications." (PMID 36541903, 2022).
pulmonary sarcoidosis (2 papers, 2015 to 2020). Sarcoidosis affecting the lung parenchyma. "Elevated expression of TREM-1 in pulmonary sarcoidosis can contribute to CD8+ T cell deletion by TREM-1 dependent perforin-granzyme mechanism." (PMID 32508528, 2020). "In pulmonary sarcoidosis, we noticed a decrease in TREM-1+CD14+ cells, CD4+ T cells, DLCO and increase in CD8+ T cells in relationship with HRCT images acquired from the most benign to the most severe type." (PMID 32508528, 2020). "In our work from 2013 we identified increased expressions of TREM-1 and TREM-2 receptors on the surface of myeloid cells and increased levels of soluble TREM-1 in bronchoalveolar lavage fluid in pulmonary sarcoidosis patients." (PMID 26166951, 2015). "The study proved increased TREM-1 expression on alveolar macrophages in pulmonary sarcoidosis and diminished TREM-1 expression in HP-Sarcoidosis: median: 76.7; HP: median: 29.9; control: median: 53.3, (sarcoidosis versus HP: p < 0.001; sarcoidosis versus control: p < 0.05)." (PMID 32508528, 2020). "Our results suggest that in cases of pulmonary sarcoidosis increase in TREM-1 expression could lead to its activation and increased production of proinflammatory cytokines promoting the development of systemic inflammation and typical systemic symptoms such as fever, weakness, and lymphadenopathy." (PMID 32508528, 2020). "Our results show differences in TREM-1 and TREM-2 expression on CD14+ cells in bronchoalveolar lavage between pulmonary sarcoidosis and HP." (PMID 32508528, 2020). "In our previous study we identified increased expressions of TREM-1 and TREM-2 receptors in pulmonary sarcoidosis (PS)." (PMID 26166951, 2015). "In our previous study we showed an increased expression of both TREM-1 and TREM-2 receptors on the surface of myeloid cells in bronchoalveolar lavage fluid (BALF) in pulmonary sarcoidosis (PS) and increased levels of soluble sTREM-1 in BALF of PS patients." (PMID 26166951, 2015). "In contrast to TREM-1, we identified significant differences in TREM-2 expressions on myeloid cell surfaces in BALF of pulmonary sarcoidosis patients." (PMID 26166951, 2015).
pulmonary tuberculosis (2 papers, 2018 to 2021). A bacterial infection that affects the lungs and is caused by Mycobacterium tuberculosis. "The association between serum soluble TREM-1 (sTREM-1) level and pulmonary tuberculosis (PTB) disease deserves investigation." (PMID 29844416, 2018). "Our previous study demonstrated that TREM-1 is highly expressed in Vδ2 T cells from patients with active pulmonary tuberculosis (TB) and that TREM-1 promotes the antigen-presenting capability of Vδ2 T cells." (PMID 34878838, 2021). "We also used immunohistochemistry (IHC) staining to investigate the presence of TREM-1-expressing cells in lung tissues from patients with pulmonary TB." (PMID 29844416, 2018). "Most importantly, we clearly identified TREM-1-expressing macrophages in lung tissues from patients with pulmonary TB." (PMID 29844416, 2018). "We also identified abundant TREM-1-expressing macrophages in lung tissue specimens from pulmonary TB patients." (PMID 29844416, 2018). "In this study, we measured the serum levels of the soluble forms of TREM-1 and TREM-2 (sTREM-2) in patients with pulmonary TB before initiating anti-TB treatment." (PMID 29844416, 2018). "Moreover, for the first time, we demonstrated the high expression of TREM-1 in macrophages from lung tissues of patients with pulmonary TB, although LTBI or non-TB, non-LTBI individuals were not included for IHC analysis." (PMID 29844416, 2018). "It is worth noting that expression of TREM-1 in lung tissue is not specific to pulmonary TB." (PMID 29844416, 2018).
renal carcinoma (2 papers, 2021 to 2024). A carcinoma arising from the epithelium of the renal parenchyma or the renal pelvis. "The involvement of TREM1 in inducing an increased inflammatory response has been linked to various cancer types, such as prostate, breast, colon, cervical, hepatocellular, lung, and renal cancers." (PMID 39149674, 2024). "Most importantly, we find increased levels of soluble TREM-1 in patients with renal carcinomas, and the analysis of TCGA data shows that patient outcomes are worse than when the tumor levels of TREM-1 are highest." (PMID 35223446, 2021).
sarcoidosis (2 papers, 2015 to 2020). Sarcoidosis is a multisystemic disorder of unknown cause characterized by the formation of immune granulomas in involved organs. "Our team has found that in cases of HP, the TREM-1 expression was significantly decreased compared with sarcoidosis." (PMID 32508528, 2020). "We found still much higher TREM-1 expression in sarcoidosis compared with HP and the difference was statistically significant (percentage of TREM-1+CD14+ cells: P = 0.0002; TREM-1 MFI P = 0.0395)." (PMID 32508528, 2020). "We found significantly higher TREM-1 expression (percentage of TREM-1+ cells) in stage I compared with stage II in sarcoidosis (P = 0.005)." (PMID 32508528, 2020). "Differences in TREM receptor expression in sarcoidosis (increase in TREM-1 and TREM-2) and HP (increase in TREM-2) and correlation analysis suggests that activation via TREM may participate in typical immunological characteristics of sarcoidosis and HP." (PMID 32508528, 2020). "Interestingly, the percentage of TREM-1+ cells in stage II of sarcoidosis was still significantly increased compared with HP (stage II sarcoidosis: median: 73.1, IQR: 20.2; HP: median: 29.9, IQR: 43.6; P = 0.0006)." (PMID 32508528, 2020). "The aim of the study was to analyse TREM-1 and TREM-2 expression to identify further molecular mechanisms participating in the immunopathogenesis of sarcoidosis and HP." (PMID 32508528, 2020). "The aim of our current study was to determine the association between the serum levels of an inactive form of 25(OH)D vitamin and TREM-1 and TREM-2 receptor expressions, which undoubtedly participate in the immune response accompanying sarcoidosis." (PMID 26166951, 2015).
tauopathy (2 papers, 2022 to 2025). Neurodegenerative disorders involving deposition of abnormal tau protein isoforms (tau proteins) in neurons and glial cells in the brain. "In female tauopathy mice, Dap12 deletion downregulated key inflammatory pathways such as cytokine storm signaling, TREM1 signaling, and interferon (IFN) responsesࣧthat are otherwise activated by tau pathology." (PMID 41331787, 2025).
Thrombosis (2 papers, 2019 to 2024). "Moreover, in vivo TREM-1 inhibition decreased thrombus formation in a carotid artery model of thrombosis and protected mice during pulmonary embolism." (PMID 30616644, 2019).